TLR4 (toll like receptor 4)
Diseases named in the same sentence as TLR4 in open-access papers (continued):
Sharing a sentence is not in itself a finding about the gene and the disease.
tumor (continued). "In xenograft models of CRC, TLR4 silencing with RNA interference decreases the metastatic tumor burden in the liver." (PMID 24887394, 2014). "In the present study, we aimed to investigate the function of TLR4/MyD88 signaling in tumor progression in both cell lines MDA-MB-231 and MCF-7, especially in tumor metastasis." (PMID 25299052, 2014). "In in vitro studies, different tumor promoting effects were directly observed when cells were exposed to the TLR4 agonist LPS." (PMID 25411122, 2014). "We focused our study on TLR4 and used the LPS ligand and antagonist eritoran to explore further the role of TLR4 in tumor metastasis." (PMID 25299052, 2014). "It was recently shown that TLR4 is involved in the invasiveness of some tumor cells triggered by endogenous and exogenous ligands." (PMID 24614130, 2014). "Correspondingly, TLR4 silencing has been shown to decrease tumor burden in a murine model of colorectal metastasis and hepatic steatosis." (PMID 25120541, 2014). "Blockade of the TLR4 pathway reverses the functions of these cells in vitro and in vivo, delays tumor growth and, thus, prolongs the survival of tumor-bearing mice." (PMID 24527095, 2014). "Other investigators have shown that α4β1 is involved in tumor progression involving the TLR4 signaling pathway and p110γ axis." (PMID 24770346, 2014). "TLR-4 signaling in cancer is considered a double-edged sword leading to both cancer inhibition and growth as not only immune cells, but also histologically different tumor cells express different levels of TLR-4." (PMID 25432242, 2014). "In our study, both cell lines were used to confirm more accurately the role of TLR4 in tumor metastasis." (PMID 25299052, 2014). "If TLR4 signaling highlights a survival benefit to tumor cells and alters their sensitivity to Pac, then its silencing via siRNA must aid in identifying the molecular mechanisms responsible for LPS- and Pac-mediated effects." (PMID 24527095, 2014). "TLR4 mRNA expression in tumor tissues from N0 to N3 was 59.29±31.93, 77.43±20.72, 87.37±17.00 and 213.71±46.79 times higher, respectively, than in normal tissue (P<0.05)." (PMID 25299052, 2014). "During radiotherapy and chemotherapy, this soluble danger signal is released from dying tumor cells, activates TLR4 signaling through its MyD88 adaptor in DCs and promotes efficient processing and cross presentation of tumor antigens." (PMID 24434638, 2014). "Using LPS-treated CD14-knockdown GC cells, these authors showed that CD14, an important co-receptor in the TLR4 complex, promotes tumor cell epithelial–mesenchymal transition and invasion through TNF-α." (PMID 25101079, 2014). "It was reported that the activation of TLR4 signaling by lipopolysaccharide protects tumor cells from immune attack and therefore induces tumor growth." (PMID 24932259, 2014). "In CRC, elevated TLR4 expression is observed in all tumor components such as the epithelial, endothelial, and stromal layers." (PMID 25076949, 2014). "In tumor cells, it is TLR4 that is activated by TNF-α, via TIR-domain-containing adapter-inducing interferon-β (TRIF) dependent pathway, forming a feed-forward loop with TNF-α, which triggers the release of these cytokines." (PMID 25411122, 2014). "TLR4 expression was universally present and scored as positive (immunoscore >4) in all tumours (20/20)." (PMID 24977712, 2014). "TLR2 and TLR4 immunoreactivity was present mainly in the tumor-infiltrating inflammatory cells (lymphocytes), which were morphologically identical to monocytes/macrophages." (PMID 25547486, 2014). "While TLR4 is predominately pro-tumorogenic, it can induce the production of interferons contributing to an anti-tumor response." (PMID 25309546, 2014). "In particular, an increased expression of TLR4 in the tumor stroma relative to the malignant epithelium was noted." (PMID 24887394, 2014).
tumor (continued). "They showed that Hsp70 produced by heated tumour cells activated tumour cells to produce chemokines that increased recruitment of DCs and CD4+ and CD8+ T cells into the tumour and that the recruitment was dependent on TLR4 expressed by tumour cells and DCs." (PMID 25430985, 2014). "The likely mechanism for paclitaxel-dependent tumor-activating effects is the ability of paclitaxel to activate TLR4/MyD88 signaling pathway." (PMID 24452475, 2014). "In tumor tissue, TLR4 was localized in the cytoplasm and cell membrane, and its expression tended to be stronger in patients with lymph node metastasis of N0, N1, N2 and N3." (PMID 25299052, 2014). "TLR4 ligation on tumor cells can enhance the secretion of immunosuppressive cytokines and induce resistance to TNF-related apoptosis-inducing ligand (TRAIL)-induced apoptosis." (PMID 24376595, 2013). "Conversely, TLR4 knock-down in PC3 cells resulted in a dramatic reduction of tumour cell viability and invasion." (PMID 23551576, 2013). "In the current study, we demonstrate the importance of TLR4, an innate immune receptor, in intestinal tumorigenesis and provide evidence that TLR4 acts as a potent tumor promoter." (PMID 23691015, 2013). "TLR4 activates β-catenin through an intracellular signaling pathway leading to increased cell proliferation and neoplasia." (PMID 23691015, 2013). "We have previously also shown that the inhibition of S100A9 and TLR4 expression influenced EL4 tumor growth, and that the inhibition of S100A9 interactions in vivo using Q compounds mimicked this effect." (PMID 23667563, 2013). "TLR4 expressed on tumor cells has been found to contribute to tumor progression by promoting tumor cell proliferation, apoptosis resistance, and tumor evasion from immune attack." (PMID 24363762, 2013). "Expression of TLR4 was also detected in several tumors and tumor cell lines and was shown to be involved in the anti-proliferative action of Pac." (PMID 23441224, 2013). "Our results described the involvement of TLR4 signaling in promoting tumor development by showing that LPS can significantly induce human GC cells to proliferate." (PMID 24030146, 2013). "In this study, our results suggested that TLR4 expression in GC correlated with tumor stages and activation of TLR4 contributed to GC cell proliferation via mROS production." (PMID 24030146, 2013). "The role of TLR4 and Nanog in this process was demonstrated by findings that when TLR4 or Nanog were silenced, the tumor-initiating properties of the TISCs were attenuated." (PMID 24313165, 2013). "Simultaneously, we established LMW-HA-W3 tumor-bearing mice model to further determine the function of the LMW-HA/TLR4/CXCR7 pathway in PTC." (PMID 24363762, 2013). "We show here that OX, which has a very similar effect on S100A9-RAGE/TLR4 interactions as Q compounds, also shows anti-tumor effect in vivo in the same tumor model." (PMID 23667563, 2013). "HSPs exposed by tumor cells can be recognized by TLR4 expressed on DCs, which facilitates activation, intracellular antigen-processing and -presentation in DCs; and CRT and HMGB1 exposed on ethanol-treated tumor cells serve “eat-me” signals." (PMID 23717436, 2013). "Given the potent tumor-prone phenotype seen in the colon of villin-TLR4 mice, we examined villin-TLR4 mice for the spontaneous development of tumors." (PMID 23691015, 2013). "In particular, it has been shown that inhibition of hS100A9/TLR4 interaction inhibited tumour growth." (PMID 23626736, 2013). "We demonstrate experimentally that TLR4 can activate the central program of cell proliferation in the intestine, the β-catenin pathway, and that over-expression of TLR4 is sufficient to make the intestinal epithelium tumor prone." (PMID 23691015, 2013). "Depletion of HMGB1 from dying tumor cells abolishes the TLR4-dependent, DC-mediated presentation of antigens from dying tumor cells in vitro and in vivo." (PMID 23251389, 2012).
tumor (continued). "It has recently been determined that the expression of TLR4 is also found in various types of tumor cells." (PMID 22583829, 2012). "Conceptually, apoptotic death of tumor cells is predicted to conceal HMGB1 from TLR4-mediated recognition." (PMID 23087904, 2012). "The ability of a tumor derived ligand for TLR4 such as Prx1 to drive VEGF expression in normoxic conditions has implications for our understanding of the role inflammation plays in tumor development and progression." (PMID 23185615, 2012). "This indicated that the molecule from tumor cells elicits an immune response involving the induction of inflammatory cytokines in a TLR4-dependent fashion." (PMID 21941554, 2012). "TLR4 expression by DCs also appears to be a prerequisite for efficient antigen presentation of tumor antigens furnished by dying cancer cells." (PMID 23251903, 2012). "In this paper, the traditional anti-tumor drug NCTD has been found as a positive regulator in TLR4 mediated anti-infection immunity." (PMID 22984593, 2012). "TLR4 protein was detected by immunohistochemistry and was localized in the cytoplasm and membrane of the tumor cells." (PMID 22985132, 2012). "Lastly, treatment of mice with a small molecule (ABR-215050) that inhibits S100A9 binding to TLR4 inhibited EL4 tumor growth." (PMID 22470535, 2012). "The combined findings of the current study and our previous study suggest that Prx1 interaction with TLR4 promotes CaP growth potentially through chronic activation of tumor angiogenesis." (PMID 23185615, 2012). "Dietary modulation of these genes in addition to a lower expression of other innate immune genes, including toll-like receptor 4 (Tlr4) and Dmbt1, further suggest bean feeding inhibits tumor promotion by limiting microbially induced inflammation." (PMID 22496968, 2012). "As EL4 tumor growth was not reduced in RAGE−/− mice, we concluded that the interaction of S100A9 with TLR4 promotes tumor growth." (PMID 23234398, 2012). "Our study for the first time revealed that TLR4, MyD88, and NF-κB were expressed in the tumor cells of a large number of OECs using immunohistochemistry." (PMID 22985132, 2012). "It was recently reported that TLR4/MyD88 signalling drives tumour growth in EOC with MyD88 positive expression." (PMID 22533866, 2012). "In tumor samples, TLR4 was found to localize to the cell membrane and cell cytoplasm and MyD88 localized to the cell cytoplasm only." (PMID 22583829, 2012). "Tumor stromal pathways are also in evidence with the common genes including; TLR4, TLR7, HLA-DRA, HLA-DQA1, CXCR4, FOS and TGFB2 (immune surveillance and chemokine pathways) and NF2, ITGA7, PGF, ITGA4, PDGFD and PARVA (focal adhesion)." (PMID 23226201, 2012). "They showed that TLR4 and MyD88 were expressed in tumor cells of OEC both at the mRNA and protein level, and that the TLR4 induces NF-κB activation in MyD88-positive OEC cells." (PMID 22985132, 2012). "Disruption of Prx1 interaction with TLR4 has the potential to inhibit Prx1 augmentation of a pro-tumor microenvironment and stimulation of tumor angiogenesis." (PMID 23185615, 2012). "Recent reports revealed that TLR4/MyD88 signalling drives tumour growth and chemoresistance to paclitaxel in EOC." (PMID 22533866, 2012). "Most of the HCC patients within the high expression group had tumor thrombus, and the IHC results showed that TLR4 expression in tumor thrombus was higher than in normal liver tissue." (PMID 22938142, 2012). "Silencing TLR4/MyD88 signalling in tumour cells results in reduced tumour formation, and the inhibition of tumour-cell apoptosis by MyD88-dependent TLR4 signalling was observed in EOC." (PMID 22533866, 2012). "We also detected the expression of TLR4 and MyD88 in the normal mucosa adjacent to the tumor, but the expression was quite weak." (PMID 22583829, 2012).
tumor (continued). "HMGB1 released by dying tumor cells after doxorubicin or oxaliplatin treatment acts upon toll-like receptor 4 (TLR4) on dendritic cells to initiate efficient antigen processing and presentation that involves the Myd88-signaling pathway." (PMID 22400040, 2012). "Toll-like receptor (TLR) pathways such as TLR4 activation on tumor cells have also been shown to directly stimulate tumor growth." (PMID 22927846, 2012). "We see that TLR4/MyD88 regulates the expression of IL-6, which shows its important role in many aspects of tumour growth." (PMID 22533866, 2012). "Individual survival pathways including the PI3K/Akt pathway, which is known to facilitate tumour metastasis, can be activated by TLR-4 signalling." (PMID 23071493, 2012). "In this study, we included a large number of cases of OECs and various histologic subtypes of OECs and tried to demonstrate the expression of TLR4/MyD88 signaling pathway proteins in tumor cells using an immunohistochemical method." (PMID 22985132, 2012). "It has been known that TLR4/MyD88 signalling in tumour cells itself has important roles as oncogenic factors." (PMID 22533866, 2012). "We also found that combined high expression of all TLR4, MD-2, and CXCR7 was significantly associated with tumor size, when compared with other combinations (p = 0.037)." (PMID 22180778, 2011). "In current study, we assessed the efficacy of an immunotherapeutic regimen consisting of the TLR4 agonist EC-LPS plus the TLR9 agonist CpG ODN against tumor metastasis." (PMID 21931823, 2011). "TLR4 is expressed in a variety of tumors, and TLR4 activation can promote development and progression, apoptosis resistance, invasion, metastasis of tumors and tumor immune escape." (PMID 22180778, 2011). "Successful activation and maturation of tumor-specific immune cells is now known to be mediated by bacterial endotoxin, which activates Toll-like receptor 4 (TLR4)." (PMID 22110526, 2011). "For the TLR4 Thr399Thr genotype the explorative statistical analysis indicated a positive correlation between AJCC tumor stage and Thr399Thr genotype only (p < 0.01)." (PMID 21854645, 2011). "Silencing of TLR4 on tumors lowered the tumor burden, indicating that tumor cell TLR4 signaling promotes metastatic growth." (PMID 22110526, 2011). "In aggregate, these results delineate a clinically relevant pathway triggered by tumor cells with an altered TLR4 SNP." (PMID 21854645, 2011). "Stimulation of TLR4 on tumor cells can give contradicting results in terms of cancer progression versus treatment." (PMID 22110526, 2011). "Yet, cancer cells ectopically expressing TLR4 do possess increased cell motility and invasiveness, both characteristic of an aggressive tumor phenotype." (PMID 21854645, 2011). "TLR4 expression was indeed observed on gastric carcinoma tumor cells as well as on gastric epithelium with intestinal metaplasia and dysplasia." (PMID 22110526, 2011). "Among those factors such as the recruitment of microenvironmental cells and the cytokines those cell secreted into the tumor microenvironment, the activation of TLR4 was considered as a two edged sword, which has both the anti-tumor and pro-tumor functions." (PMID 22195048, 2011). "TLR4 is expressed on a variety of immune as well as tumor cells, but its activation can have opposing effects." (PMID 22110526, 2011). "While TLR4 activation can promote antitumor immunity, it can also result in increased tumor growth and immunosuppression." (PMID 22110526, 2011). "Concomitant and high expression of both markers TLR4/MD-2 was more predictive of tumor size and lymph node involvement." (PMID 22180778, 2011). "They demonstrated that TLR4 is essential for efficient tumor antigen cross-presentation following radio- or chemotherapy and proposed that HMGB1 binds and activates TLR4 on DCs." (PMID 22110526, 2011).
tumor (continued). "Further, TLR4 ligation on HNSCC cells with LPS induced tumor promotion by enhancing proliferation, activation of NFκB and resistance to NK cell mediated cytotoxicity." (PMID 21854645, 2011). "On colon carcinoma cells TLR4 signaling, in addition to production of immunosuppressive factors, also improved tumor cell apoptosis resistance." (PMID 22110526, 2011). "TLR4 expression by tumor cells can be a contributing factor that promotes tumor cell proliferation, survival, or immunosuppression." (PMID 22110526, 2011). "The interaction of HMGB1 released from dying tumor cells with Toll-like receptor 4 (TLR4) on dendritic cells (DCs) was required for the cross-presentation of tumor antigens and the promotion of tumor specific cytotoxic T-cell responses." (PMID 20579387, 2010). "Tumors with high TLR3 expression by tumor cell or with high TLR4 expression by mononuclear inflammatory cells were significantly associated with higher probability of metastasis." (PMID 21129170, 2010). "Taken together, the recent data suggest that alcohol and HCV NS5A induce synergistic tumor development via induction and activation of TLR4 in mice and that this synergism involves the stem cell marker Nanog, which is a TLR4-downstream regulated gene." (PMID 20827314, 2010). "We see that TLR4/MyD88 regulates the expression of Cox-2, which shows its important role in many aspects of tumour growth." (PMID 20145615, 2010). "Silencing TLR4/MyD88 signalling in tumour cells not only results in reduced tumour formation but also leads to prolonged survival after subcutaneous tumour injection in mice." (PMID 20145615, 2010). "When we examined the endothelial compartment, we also found a trend towards an increase in TLR-4-expressing cells paralleling tumor progression." (PMID 21059221, 2010). "TLR-4 and IL6 expression in the tumor microenvironment were associated with adenocarcinoma in human samples and in the murine model." (PMID 21059221, 2010). "Statistically significant results were obtained for TLR-4 expression in the tumor stroma compartment." (PMID 21059221, 2010). "This study, for the first time, showed the clinicopathological significance of tumour cell self-TLR4/MyD88 expression in CRC." (PMID 20145615, 2010). "An interesting recent study found that the release of HMGB1, a TLR4 agonist, from dying tumor cells stimulated dendritic cells to initiate an adjuvant anti-tumor immune response in a TLR4 dependent fashion." (PMID 22069563, 2010). "TLRs are also expressed on the tumor cell surface, and the incidence of lung cancer in TLR4 mutant mice is 60% more than in normal mice." (PMID 20089147, 2010). "Toll-like receptor 4 (TLR4) signaling in tumor cells can mediate tumor cell immune escape and tumor progression, and it is regarded as one of the mechanisms for chronic inflammation in tumorigenesis and progression." (PMID 20618976, 2010). "Blockage of TLR4 signaling has been shown to delay tumor growth and prolong the survival of animals." (PMID 20618976, 2010). "Although the anti-cancer mechanism of action of paclitaxel is initially due to effects on β-tubulin, growing evidence supports anti-tumor effects through innate immune activation and possibly through TLR4/MD-2 activation." (PMID 20653948, 2010). "The aim of this study, therefore, was to determine if the u-PA system is involved in endotoxin-enhanced tumour cell adhesion and extracellular invasion, and to elucidate the function of TLR-4 and NF-κB in this process." (PMID 19436306, 2009). "TLR-4 blockade also significantly reduced LPS-dependent tumour cell vitronectin adhesion and in vitro tumour cell invasion for SW480 and SW620 cell lines." (PMID 19436306, 2009). "Certain innate sensors, such as nod1, appear to prevent tumour development; others, such as tlr4 and myd88, promote carcinogenesis." (PMID 19672421, 2009).